MYMX (myomixer, myoblast fusion factor)
Description:
Myoblast-specific protein that mediates myoblast fusion, an essential step for the formation of multi-nucleated muscle fibers. Involved in membrane fusion downstream of the lipid mixing step mediated by MYMK (By similarity). Acts by generating membrane stresses via its extracellular C-terminus, leading to drive fusion pore formation. Acts independently of MYMK (By similarity). Involved in skeletal muscle regeneration in response to injury by mediating the fusion of satellite cells, a population of muscle stem cells, with injured myofibers (By similarity).
Synonyms: hMINION; MINION; CFZS2
Gene: Protein-coding gene on chromosome 6 (44,216,926 to 44,218,236, forward strand). Ensembl gene ENSG00000262179.
Subcellular location: Cell membrane
Subcellular location (Human Protein Atlas): Vesicles; Cytosol; Mitochondria
Gene Ontology:
Biological process: myoblast fusion; myoblast fusion involved in skeletal muscle regeneration; skeletal muscle organ development; skeletal muscle tissue regeneration
Cellular component: endoplasmic reticulum membrane; Golgi membrane; plasma membrane
Homologues: Orthologues: chimpanzee MYMX (98% identical), pig MYMX (85% identical), rabbit MYMX (81% identical), dog MYMX (80% identical), mouse Mymx (79% identical), rat Mymx (76% identical).
Diseases named in the same sentence as MYMX in open-access papers:
MYMX is named in the same sentence as 4 diseases in open-access papers, as found by Europe PMC text mining. Sharing a sentence is not in itself a finding about the gene and the disease. The quoted sentences say what the papers report.
congenital myopathy (2 papers, 2022 to 2024). "Here we show the involvement of MYMX, an essential muscle fusogen, in the etiology of CFZS, a progressive congenital myopathy with developmental defects." (PMID 35642635, 2022).
myopathy (1 paper, 2022). A disease of the muscle in which the muscle fibers do not function properly. "MYOMAKER (MYMK) and MYOMIXER (MYMX) are proteins that harbor fusogenic activity and mutations in MYMK and MYMX result in a clinical myopathy known as Carey-Fineman-Ziter syndrome." (PMID 36400788, 2022).
neuromuscular disease (1 paper, 2022). "Our findings identify MYMX as a recessive, monogenic human disease gene involved in CFZS, and provide new insights into the contribution of myoblast fusion to neuromuscular diseases." (PMID 35642635, 2022).
MYMX also shares sentences with these, for which no sentence is quoted: facial nerve palsy (1 paper).